THBS1 (thrombospondin 1)
Diseases named in the same sentence as THBS1 in open-access papers (continued):
Sharing a sentence is not in itself a finding about the gene and the disease.
Peri-Implantitis (1 paper, 2023). An inflammatory process with loss of supporting bone in the tissues surrounding functioning DENTAL IMPLANTS. "Taken together, the results indicate that m6A modification of mRNA plays a vital role in MC3T3-E1 cells under hypoxia, and YTHDF1 with its downstream THBS1 might provide potential candidates for the treatment of hypoxia-induced bone loss in peri-implantitis." (PMID 36675257, 2023). "According to the findings of our results, we hypothesized that YTHDF1 regulates Thrombospondin-1 (THBS1) post-transcriptionally through m6A methylation to promote osteogenic differentiation of MC3T3-E1 cells, providing an important potential for the treatment of peri-implantitis." (PMID 36675257, 2023). "The limitation of our study is that the downstream targets of YTHDF1 may not be limited to THBS1, and further studies that explore other downstream targets of YTHDF1 are required for a better understanding of the role of YTHDF1 in the pathogenesis of peri-implantitis." (PMID 36675257, 2023).
Peters plus syndrome (1 paper, 2016). "THBS1 which has been shown to play a role in the etiology of Peters-plus syndrome (OMIM #261540) with OFC as one of the clinical features is deleted in two CP patients." (PMID 26561393, 2016).
promyelocytic leukemia (1 paper, 2022). "The functional glycoprotein, thrombospondin-1 triggers caspase free cell death in promyelocytic leukemia NB4 cells and freshly isolated monocytes and monocyte-derived dendritic cells through thrombospondin-1 membrane receptors CD47 and α vβ3." (PMID 36234938, 2022).
prostate (1 paper, 2024). "Thrombospondin-1 (THBS1) and cathepsin D (CTSD) are two glycoproteins identified to be associated with prostate carcinogenesis by mass spectrometry-based proteomics." (PMID 39081487, 2024).
prostate adenocarcinoma (1 paper, 2021). "Here, we found downregulated methylation of THBS1 in BRCA, THBS2 in KIRC, and THBS4 in PRAD (prostate adenocarcinoma) and LIHC (liver hepatocellular carcinoma)." (PMID 34804159, 2021).
pulmonary tuberculosis (1 paper, 2024). A bacterial infection that affects the lungs and is caused by Mycobacterium tuberculosis. "To further explore the possibility of targeting THBS1/2 for the treatment of granulomatous fibrosis, we developed an in vitro model of pulmonary tuberculosis by co-culturing macrophages and pulmonary organoids infected with Mtb." (PMID 39431015, 2024).
renal tumors (1 paper, 2010). "Notably, several key genes involved in TGF-β signaling, such as TGFB2, INHBA, THBS1 and SMAD3, were down-regulated in FLCN-null and mutant FLCN cells as well as in the BHD-associated renal tumors." (PMID 20573232, 2010). "GREM1, TGFB2, INHBA, THBS1 and SMAD3 RNA expression levels were significantly lower in the BHD renal tumors compared to normal kidney tissue." (PMID 20573232, 2010).
retinopathy of prematurity (1 paper, 2017). A bilateral retinopathy characterized by neovascularization, scarring, retinal detachment, and eventually blindness. "Levels of THBS1, MMP8, MMP9, MMP25, TIMP2 and TIMP3 increased as severity of BPD and retinopathy of prematurity (ROP) increased, whereas ETS1, LEF1 and SPOCK2 exhibited the opposite trend." (PMID 28103583, 2017).
rheumatic diseases (1 paper, 2020). "Therefore, low density lipoprotein related protein 1 (LPR-1), thrombospondin-1 (TSP-1), voltage dependent anion channel 2 (VDAC2) and annexin A1 were chosen as proteins of special interest, based on literature data supporting their involvement in arthritic and rheumatic diseases." (PMID 32586320, 2020).
sarcoidosis (1 paper, 2025). Sarcoidosis is a multisystemic disorder of unknown cause characterized by the formation of immune granulomas in involved organs. "While MET is a hallmark of tissue granuloma formation, blood monocytes in both active TU and sarcoidosis exhibited epithelial–mesenchymal transition (EMT) signatures, including significantly increased expression of GADD45B, CD44, CXCL8, ANPEP and THBS1,30, 31, 32, 33 compared with healthy donors." (PMID 40469525, 2025).
signet ring cell carcinoma (1 paper, 2022). A usually aggressive, poorly differentiated invasive adenocarcinoma characterized by the presence of malignant glandular cells in which the nucleus is pressed to one side by the presence of intracytoplasmic mucus. "Expression of THBS1 and SERPINE1 in signet-ring cell carcinoma and non-signet ring cell carcinoma." (PMID 35372476, 2022).
silicosis (1 paper, 2021). Silicosis is a respiratory disease caused by breathing in (inhaling) silica dust. "Furthermore, the transcriptional factor related to cell-to-matrix interactions, THBS1, was significantly higher in PBMCs from patients with silicosis." (PMID 34517882, 2021). "The results indicated that the expression of SMAD2, MAPK3, THBS1, ITGB3, and BMP4 was increased, while the expression of SMAD3 and CD44 was significantly low expression in PBMCs from patients with silicosis, indicating consistent results with the RNA-Seq data." (PMID 34517882, 2021).
soft tissue sarcoma (1 paper, 2009). A malignant neoplasm arising from muscle tissue, adipose tissue, blood vessels, fibrous tissue, or other supportive tissues excluding the bones. "The outcome of a phase II study investigating the efficacy of a THBS-1 mimetic (ABT-510) in soft tissue sarcoma showed safety but no compelling evidence for use as a single agent." (PMID 19738618, 2009).
spondylolisthesis (1 paper, 2025). A condition in which there is forward displacement of a vertebral bone over the on below it. "The predominant NPPCs in C2 exhibit osteogenic features, with high expression of genes such as BMP4, TGFB2, and THBS1, indicating an adaptive response to spinal instability, which is often linked with spondylolisthesis." (PMID 40883814, 2025).
thrombotic disease (1 paper, 2022). The formation of a blood clot in the lumen of a vessel or heart chamber; causes include coagulation disorders and vascular endothelial injury. "Future studies should shed light on the contribution of thrombospondin-1 in platelet activation and thrombus formation; in fact, targeting the thrombospondin-1 pathway may represent a promising thrombolytic strategy for controlling platelet activation in thrombotic diseases." (PMID 35682744, 2022).
Wilms tumor (1 paper, 2013). An embryonal neoplasm characterized by the presence of epithelial, mesenchymal, and blastema components. "To confirm the specificity of THBS1 hypermethylation in CCSK among pediatric renal tumors, we additionally analyzed Wilms’ tumor and CMN." (PMID 23638012, 2013). "When we analyzed 6 each of RTK, CCSK, ESFT, and NK as well as 21 cases of Wilms’ tumor and 9 cases of CMN, the CpG sites of THBS1 were unmethylated in all of the cases, indicating that the CpG sites of THBS1 are specifically hypermethylated in CCSK among pediatric renal tumors." (PMID 23638012, 2013). "Furthermore, THBS1 CpG sites were found to be specifically hypermethylated in CCSK and, thus, the DNA methylation status of these THBS1 sites alone was sufficient for the distinction of CCSK from other pediatric renal tumors, including Wilms’ tumor and CMN." (PMID 23638012, 2013). "Furthermore, the DNA methylation status of the THBS1 CpG site detected by COBRA alone can distinguish CCSK cases from other pediatric renal tumors, including Wilms’ tumor and CMN." (PMID 23638012, 2013).
ZIKV infection (1 paper, 2025). "Moreover, by understanding how mosquito cells respond to ZIKV infection, some key genes such as ITGAL, CXCL8, and THBS1 may be targeted to disrupt the virus’s replication or transmission." (PMID 40927453, 2025).
tumor (540 papers, 1995 to 2026). "THBS1, a 450-kDa extracellular matrix glycoprotein secreted by endothelial cells, fibroblasts, macrophages, monocytes, and some tumor cells, is associated with various cancer types." (PMID 40988744, 2025). "THBS1 also promotes tumor metastasis in post-dormancy stages of PDAC by converting latent TGF-β1 complexes to their active form through loss of the tumor suppressor Smad4 and upregulation of MMP-9 production." (PMID 40507347, 2025). "Elevated levels of THBS1 in GC are linked to tumor development, cell adhesion, and notable immune system involvement, marking it as an independent risk factor." (PMID 38761291, 2024). "As expected, BA-treated tumours had reduced expression of TGF-β target genes (Thbs1, Vegfa, Runx1), as well as genes linked to ascites production (Vegfa)." (PMID 38622286, 2024). "THBS1 is most commonly used as an anti-angiogenic factor, but it is positively associated with poor tumor prognosis." (PMID 39040110, 2024). "Their findings revealed that elevated tumor expression levels of five markers including THBS‐1 were significantly associated with poor disease‐free survival and an increased risk of disease progression or recurrence." (PMID 38946720, 2024). "The expression of THBS1 is particularly strongly associated with tumor-associated macrophages (TAM), M2 macrophages, and cancer-associated fibroblasts (CAF) within GC." (PMID 38761291, 2024). "THBS1 is often found to be associated with tumor progression, metastasis, and therapy resistance in many different types of cancers." (PMID 39133651, 2024). "THBS1 is a multifunctional glycoprotein that acts as an inhibitor of angiogenesis and participates in tumor progression, where its overexpression is associated with tumor differentiation." (PMID 39456895, 2024). "THBS1 encodes thrombospondin-1, a secreted protein in the tumor microenvironment, which is upregulated in response to lactate, leading to increased secretion of TGF-β2 and enhanced migration of glioma cells." (PMID 38365809, 2024). "Intriguingly, THBS1 loss induced distinct tumor and immune phenotypes in primary and metastatic lesions." (PMID 37749092, 2023). "This is relevant because, according to the Gene Cards Human Gene Database, overexpression of RHOA is associated with tumor cell proliferation and metastasis, while THBS1 plays a role in platelet aggregation, angiogenesis, and tumorigenesis." (PMID 35628184, 2022). "It has been proposed that the association between CD47 on tumor cells and thrombospondin-1 on T cells acts as an immunological checkpoint, impairing T cell activation and thereby decreasing antigen-dependent killing of tumor cells by CD8+ T cells." (PMID 35865547, 2022). "And LAMC1 was associated with feature ‘Rectlike’ and ‘deviation ratio of tumor and normal thyroid gland’ (p<0.001; p<0.001); THBS1 was correlated with ‘minimum calcification area’ (p<0.001)." (PMID 34268116, 2021). "Another study suggests that inhibition of tumor growth by THBS1 is thought to be associated with its antiangiogenic activity." (PMID 34390026, 2021). "Univariate analysis showed that THBS1 methylation levels in tumor tissues or PPLF or serum were significantly associated with adverse prognosis in GC (all p < 0.0001)." (PMID 34390026, 2021). "THBS1, known as encoding thrombospondin 1, plays a vital role in angiogenesis and tumor progression, overexpression of which was significantly associated with tumor differentiation." (PMID 35237609, 2021). "Out of nine genes differentially expressed in our study, five are included in the PI3K-AKT pathway, with three of them—FN1, NGFR, and THBS1—being associated with tumor progression." (PMID 32093414, 2020). "As for THBS1, encoding thrombospondin 1, it took part in angiogenesis and tumor progression, whose increased expression was significantly correlated with tumor differentiation." (PMID 33178362, 2020).
tumor (continued). "As such, angiogenic factors display a reduced expression in dormant cells; meanwhile, the high transcription level of angiogenesis inhibitors such as angiostatin, endostatin, and thrombospondin-1 is associated with the tumor dormancy." (PMID 31430951, 2019). "THBS1 underlies the inhibitory role of BMP4 in tumor angiogenesis, which is mainly achieved by a network that VEGF expression is reduced by BMP4 in a THBS1-dependent manner in the tumor microenvironment." (PMID 31847842, 2019). "THBS1 has previously been associated with the development of the tumor micro-environment and angiogenesis and metastasis." (PMID 29986714, 2018). "THBS1 is an antitumorigenic factor essential for normal prostate angiogenesis whose loss has been linked to both tumor progression and enhanced VEGF expression." (PMID 26588813, 2016). "The dysregulation of cell energy metabolites was associated with increased tumor multiplicity and decreased survival of ApcMin/+:Thbs1−/− mice when fed a low-fat diet." (PMID 27239962, 2016). "THBS1 is a known angiogenesis inhibitor associated with neovascularization in human cancer, its expression associated with tumor malignance in UTUC." (PMID 25613404, 2015). "Nonetheless, ADAMTS-1 can also generate anti-angiogenic peptides through the digestion of thrombospondin-1 or endorse the recruitment of fibroblasts involved in tumor growth, an effect also associated to an increased deposition of collagen-1." (PMID 24457941, 2014). "THBS1 is a matricellular protein capable of modulating angiogenesis, and high expression of THBS1was shown to be associated with tumor invasiveness and progression in HCC." (PMID 24083576, 2013). "There are several reports suggesting that reduced expression of THBS1 or hypermethylation of THBS1 is associated with poor prognosis of cancer patients and higher tumor grade." (PMID 20573232, 2010). "Angiogenesis is a hallmark of KS tumors, and the inhibition of THBS1 would aid not only this process but also proliferation of KSHV-infected endothelial-derived KS tumor cells." (PMID 17500590, 2007). "In gynecological tumors, plasma levels of THBS1 are associated with tumor grading." (PMID 41438033, 2025). "In the context of TNBC, THBS1 could be secreted by tumor cells, cancer-associated fibroblasts (CAFs), and immune cells such as macrophages and dendritic cells, particularly in response to hypoxia or stress signals within the tumor microenvironment." (PMID 40229283, 2025). "THBS1 can participate in important physiological processes, such as embryonic development, neovascularisation, and tissue repair, but it is also closely associated with the development of many diseases, especially tumours." (PMID 39796249, 2025). "Given the role of cytotoxic T cells in preventing tumor progression, we investigated whether THBS1-deficiency in the TME suppresses the metastasis of mesenchymal CRC." (PMID 37749092, 2023). "Moreover, ECM-related proteins (Col1A, Integrinα-V, Versican, THBS1) were associated with tumor suppression and better outcome in CLL13." (PMID 36899005, 2023). "Interestingly, patients who completed therapy showed significantly higher baseline serum THBS1 levels than patients who discontinued treatment (median 9163 vs. 4299 ng/mL), suggesting an association with tumor susceptibility to antiangiogenic therapy." (PMID 36362482, 2022). "In addition, increased expression of THBS1 has also been reported to be associated with tumour invasiveness and metastasis." (PMID 30055645, 2018). "Neutralization of thrombospondin-1 restores tumor growth in PPARα-deficient mice." (PMID 17327920, 2007). "Notably, tumour growth was even more rapid in mice deficient in both tumstatin and thrombospondin-1, indicating that these three molecules suppress the growth of tumour xenografts when present at physiological concentrations." (PMID 16234821, 2005).
tumor (continued). "Furthermore, changes in the transcriptional expression of C-Man-Trp metabolism-related genes, C-mannosyltransferases (Dpy19l1 and Dpy19l3), and thrombospondin type I repeat superfamily genes (Thbs1, Spon1, and cellular communication network factor 1) were noted in tumor-associated cells and tissues." (PMID 41812877, 2026). "Moreover, overexpressing PTEN in a PTEN-deficient glioma model significantly reduced tumor growth in vivo and increased mice survival, which was due to the induction of a negative regulator of angiogenesis, thrombospondin-1 which led to decreased blood vessel formation in the tumor." (PMID 37533462, 2023). "We propose that EV associated THBS1 may drive tumor aggressiveness and NED in advanced PCa." (PMID 33859239, 2021). "Functional experiments further confirmed that THBS1 knockdown mimics the anti-tumour effects of DMC-GF, whereas THBS1 overexpression partially mitigates its inhibitory actions." (PMID 41807988, 2026). "Thbs1 is a ligand for CD36 and CD47 receptors and it is implicated in angiogenesis, tumor growth and thromboembolism." (PMID 40841769, 2025). "Tumor cells also stimulate MDSCs to produce thrombospondin 1 (THBS1), which contributes to the development of a metastasis-resistant microenvironment." (PMID 39930476, 2025). "NETs, in turn, enhance tumor growth by degrading antiangiogenic molecules such as thrombospondin-1, thereby fostering angiogenesis and vascular remodeling." (PMID 41303697, 2025). "A pioneering study explored the interaction of endothelial and tumor cells in this context and identified thrombospondin-1 (THBS1) as an endothelial-derived mediator of tumor dormancy." (PMID 41185039, 2025). "THBS1 plays multiple roles in promoting malignancy, including by suppressing angiogenesis to promote dormancy and allowing tumor cells to escape detection by the immune system." (PMID 41294700, 2025). "This highlights prosaposin and THBS1 as potential therapeutic targets for inhibiting tumor metastasis." (PMID 39930476, 2025). "Further studies are needed to determine the precise sources and functional contributions of THBS1 within MGAT1high and MGAT1low tumor regions." (PMID 40229283, 2025). "Metronomic chemotherapy with low-dose cyclophosphamide upregulates the antiangiogenic protein thrombospondin-1, with consequent apoptosis of endothelial cells and suppression of tumor growth." (PMID 39858283, 2025). "The gene (THBS1) also facilitates cancer cell survival and tumor progression by creating a pro-angiogenic and immunosuppressive microenvironment." (PMID 40127075, 2025). "We found that arsenic sulfide has the ability to attract cytotoxic CD8+ T cells into the HCC microenvironment and reduce the expression of THBS1 in tumor through the STAT3-THBS1 signaling pathway." (PMID 41019041, 2025). "Among the upregulated proteins, we observed significant elevation of extracellular matrix proteins, including FN1 (Fibronectin 1) and THBS1 (Thrombospondin 1), which are established mediators of tumor invasion and metastasis." (PMID 40861812, 2025). "Analysis of tumor lysates from Vehicle +IgG (M1, M2) and arsenic sulfide-treated (M3, M4) mice showed an obvious decrease in the expression of THBS1 proteins." (PMID 41019041, 2025). "The role of THBS1 in cancer is complex and appears to be highly dependent on the tumor type and stage." (PMID 41019041, 2025). "Relevant studies have found that THBS1 in tumors can promote tumor metastasis by inducing cytotoxic T cell depletion." (PMID 40941025, 2025). "Mechanistic insights indicate that arsenic sulfide inhibits STAT3 phosphorylation, reduces THBS1 transcription, thereby disrupting the binding between tumor cell THBS1 and T cell CD47, consequently enhancing anti-PD-1 efficacy." (PMID 41019041, 2025). "In animal study, THBS1 inhibits angiogenesis and tumor growth but promotes metastasis to the lung, and both pro- and anti-metastasis was reported." (PMID 40927672, 2025).